WBP2 (WW domain binding protein 2)
Description:
Acts as a transcriptional coactivator of estrogen and progesterone receptors (ESR1 and PGR) upon hormone activation. In presence of estrogen, binds to ESR1-responsive promoters. Synergizes with YAP1 to enhance PGR activity. Modulates expression of post-synaptic scaffolding proteins via regulation of ESR1, ESR2 and PGR (By similarity).
Synonyms: WBP-2; GRAMD6; DFNB107
Tractability: PROTAC: ubiquitination databases record sites on it; its protein half-life has been measured.
Gene: Protein-coding gene on chromosome 17 (75,845,699 to 75,856,507, reverse strand). Ensembl gene ENSG00000132471.
Subcellular location: Cytoplasm; Nucleus
Subcellular location (Human Protein Atlas): Cytosol; Nucleoplasm
Gene Ontology:
Molecular function: chromatin DNA binding; nuclear estrogen receptor binding; protein binding; RNA polymerase II cis-regulatory region sequence-specific DNA binding; transcription coactivator activity
Biological process: cellular response to estrogen stimulus; establishment of protein localization to chromatin; positive regulation of intracellular estrogen receptor signaling pathway; positive regulation of transcription by RNA polymerase II; progesterone receptor signaling pathway; response to estrogen; response to progesterone; transcription initiation-coupled chromatin remodeling; positive regulation of DNA-templated transcription
Cellular component: chromatin; cytoplasm; cytosol; nucleoplasm; nucleus
Genetic constraint (gnomAD): Loss-of-function variants: 23 observed, 30.23 expected, observed/expected ratio (o/e) 0.76, 90% interval 0.55 to 1.08. The upper end of that interval is the gene's LOEUF score, 1.08, which puts it in group 4 of 6, group 1 being the genes least tolerant of losing a copy. Missense variants: 353 observed, 348.89 expected, observed/expected ratio (o/e) 1.01, 90% interval 0.93 to 1.11. Synonymous variants: 153 observed, 128.94 expected, observed/expected ratio (o/e) 1.19, 90% interval 1.04 to 1.36.
Gene-disease validity (ClinGen):
ClinGen rates the evidence that WBP2 causes each of these diseases.
hearing loss, autosomal recessive (autosomal recessive): Limited.
Homologues: Orthologues: chimpanzee WBP2 (100% identical), guinea pig WBP2 (97% identical), mouse Wbp2 (97% identical), rat Wbp2 (97% identical), macaque WBP2 (94% identical), dog WBP2 (92% identical), pig WBP2 (85% identical), zebrafish wbp2 (65% identical), Drosophila melanogaster Wbp2 (44% identical), Caenorhabditis elegans C18B2.4 (33% identical), Caenorhabditis elegans wbp-2 (29% identical). Paralogues in human: WBP2NL (41% identical).
Diseases named in the same sentence as WBP2 in open-access papers:
WBP2 is named in the same sentence as 52 diseases in open-access papers, as found by Europe PMC text mining. Sharing a sentence is not in itself a finding about the gene and the disease. The quoted sentences say what the papers report.
breast carcinoma (25 papers, 2017 to 2026). "In breast cancer, although GPS1 has been shown to be associated with WBP2-mediated activation of the Wnt signaling pathway, its specific molecular regulatory mechanism in breast cancer is unclear." (PMID 38289496, 2024). "Immunohistology analysis of clinical breast specimens revealed that WBP2 is upregulated in more than 80% of breast cancer patients, and positively associated with poorer prognosis." (PMID 34197030, 2022). "This suggests that the mechanism behind tamoxifen resistance in breast cancer cells can be deciphered by altering the association between WBP2 and miR-206." (PMID 34944633, 2021). "Future clinical studies correlating the ITCH mutational status with WBP2 protein expression would offer greater clarity on the prevalence of the ITCH/WBP2 signaling axis on breast cancer." (PMID 32393834, 2020). "Increased WBP2, which functions as the transcriptional coactivator of ERα/progesterone receptor (PR) transactivation, was associated with poor prognosis in ER+ breast cancer patients." (PMID 31590453, 2019). "The correlation analysis using image pro plus and SPSS software showed that the number of WBP2-positive cells was positively associated with MDR1-expressed cells in these breast cancer samples." (PMID 29937544, 2018). "Therefore, our findings concur with the notion that WBP2 is positively associated with BTRC in breast cancer, especially in TNBC." (PMID 34197030, 2022). "Therefore, the WBP2/BTRC/IκBα signaling axis was associated with poorer survival outcomes in clinical breast cancer, especially in basal breast cancer, in congruence with the findings presented in this study." (PMID 34197030, 2022). "The overall and nuclear expression of WBP2 was also positively associated with tumour size and grade, while nuclear WBP2 levels were negatively correlated with overall and disease-free survival in breast cancer patients." (PMID 34831354, 2021). "Besides the ER signaling pathway, the Wnt signaling pathway is also strongly implicated in breast cancer, and is likely to be an established element in WBP2-mediated breast cancer biology." (PMID 28724435, 2017). "The potential utilization of anti-WBP2 inhibitors as combinatorial therapy treatment is conceived from the observations that loss of WBP2 can increase sensitivity towards certain chemotherapeutic drugs such as doxorubicin, tamoxifen and trastuzumab in breast cancers." (PMID 34831354, 2021). "The effect of WBP2 on breast cancer response to metformin was studied using in vitro and mouse models." (PMID 41744824, 2026). "RNA-seq analysis revealed the potential mechanism of WBP2 in regulating ATP production processes and preferential effect of WBP2 on metformin response in HER2+ breast cancer." (PMID 41744824, 2026). "In MCF7 breast cancer cells, the interaction of ERα with WW domain-binding protein 2 (WBP2) actively modulates MDR1 expression and contributes to doxorubicin resistance." (PMID 40806331, 2025). "WBP2 is highly expressed in breast cancer tissues, and overexpression of WBP2 upregulates the ER and Wnt signaling pathways." (PMID 38239300, 2024). "In breast cancer, physical binding of WBP2 with the components of the microprocessor complex such as DDX5 and DGCR8 led to a reduction in pri-miRNA processing." (PMID 38473318, 2024). "WW‐domain‐binding protein 2 (WBP2) is a transcriptional coactivator that drives breast cancer progression." (PMID 34197030, 2022). "Together, all these findings provided evidence that WBP2 promotes breast cancer by downregulating IκBα through driving BTRC expression." (PMID 34197030, 2022). "Clinically, the WBP2‐BTRC‐IκBα signaling axis correlates with poorer prognosis in breast cancer patients." (PMID 34197030, 2022). "Since WBP2 has the highest amplification frequency in breast cancer, we proceeded to study the effects of WBP2 in breast cancer." (PMID 34197030, 2022).
breast carcinoma (continued). "To better understand the molecular etiology of WBP2 in breast cancer, we attempt to validate potential molecular mechanisms of WBP2 by performing integrated proteogenomic analysis on TCGA BRCA." (PMID 34197030, 2022). "A substantial evidence has highlighted the role of WBP2 in metastasis in HER2‐positive breast cancer and lung carcinoma in vivo." (PMID 34197030, 2022). "Consistently, we observed that combinatorial gene expression of WBP2, BTRC, and inverted IκBα associates with poorer prognosis in clinical breast cancer patients." (PMID 34197030, 2022). "Here, we identified a previously unexplored role of WBP2 in inflammatory signaling in breast cancer via an integrated proteogenomic analysis of The Cancer Genome Atlas Breast Invasive Carcinoma (TCGA BRCA) dataset." (PMID 34197030, 2022). "WBP2 has oncogenic potential, and its overexpression is observed in estrogen receptor positive (ER+) breast cancer where it promotes proliferation and facilitates the development of malignancy by activating oncogenes." (PMID 34944633, 2021). "Consistently, the higher expression of MST1/2 substantially attenuated WBP2-driven breast cancer growth in vivo and in vitro." (PMID 34831354, 2021). "Transcriptional coactivator WW domain-binding protein 2 (WBP2) is a newly discovered oncogene that has an important relationship with the occurrence and development of breast cancer and mediates the interaction between Wnt and various other signaling pathways." (PMID 33658485, 2021). "A significant inverse association between WBP2 and MST1/2 or miR-23a was observed in clinical breast cancer specimens, hence substantiating the relevance of the MST1/2–Dicer–miR-23a–WBP2 axis in breast cancer." (PMID 34831354, 2021). "Using an isogenic MCF-10AT breast cancer progression model, WBP2 was shown to be hyperphosphorylated with increasing stage progression through phosphoproteomic analysis." (PMID 34831354, 2021). "In line with these clinical studies, WBP2 has been reported to be frequently amplified or gained in multiple breast cancer databases including TCGA BRCA and METABRIC datasets." (PMID 34831354, 2021). "Previous reports depicted various mechanisms by which WBP2 exerts its oncogenic properties in breast cancer." (PMID 34117091, 2021). "Immunoprecipitation experiments in multiple breast cancer cell lines revealed the interaction of WBP2 with several MPC components, such as DGCR8, Drosha, DDX5 and DDX17." (PMID 34831354, 2021). "In vitro analysis in a breast cancer cell-line panel revealed an upregulation of the WBP2 protein level in the cancerous cell lines, as compared to the normal mammary cells." (PMID 34831354, 2021). "Collectively, these findings suggest that WBP2 is a bona fide oncogene in multiple cancer types besides breast cancer." (PMID 34831354, 2021). "Previous studies have suggested that WBP2 localizes within the nucleus of breast cancer cells and acts as a co-activator of YAP21–24." (PMID 33837178, 2021). "In breast cancer, WBP2 can combine with YAP and act as a bridge connecting the Hippo and Wnt/β-catenin pathways." (PMID 33658485, 2021). "In breast cancer, ectopic introduction of the phosphomimic mutant of WBP2 (Y192E, Y231E) was more efficacious in promoting WBP2 nuclear accumulation and the transcriptional activity of ER and β catenin." (PMID 34831354, 2021). "The expression of WBP2 correlates positively and significantly with tumor size and grade, and negatively with disease-free and overall survival of breast cancer patients including those with HER2-positive breast cancer." (PMID 34117091, 2021). "The oncogenic roles of WBP2 were initially studied in breast cancer and subsequently explored in other cancers such as squamous cell carcinoma, brain, liver, gastric and lung cancers." (PMID 34831354, 2021). "Clinical studies have found that patients with increased WBP2 expression in breast cancer patients have a relatively poor prognosis." (PMID 33658485, 2021).
breast carcinoma (continued). "WBP2 overexpression was detected in 85% of breast cancer samples compared to their normal mammary counterparts." (PMID 34831354, 2021). "The authors showed that knockdown of WBP2 and overexpression of miR-206 rendered breast cancer cells less resistant to tamoxifen." (PMID 34944633, 2021). "For example, the 3′UTR region of WBP2 has been demonstrated to be targeted by miR-206, miR-613, and miR-23a in breast cancer, and miR-458 in hepatocellular carcinoma." (PMID 34117091, 2021). "Lim and colleagues found that silencing of AIP4 blocks ubiquitin-dependent proteasomal degradation of the YAP/TAZ transcriptional coactivator WBP2 as well as promotes anchorage-independent colony and in vivo tumor growth in breast cancer." (PMID 35177982, 2021). "The mechanism of action of WBP2 in promoting breast cancer was elucidated to be dependent on Wnt-induced nuclear entry and interaction of WBP2 with β-catenin, which complexes with TCF to activate gene transcription." (PMID 32393834, 2020). "The elevated expression of WBP2 conferred to breast cancer cells a higher response to trastuzumab increasing HER2 downregulation and cell-cycle arrest." (PMID 32210163, 2020). "In conclusion, the Hippo/MST pathway is established to modulate breast cancer by controlling the expression of WBP2 via a novel mechanism involving Dicer." (PMID 32820148, 2020). "Since WBP2 protein is well established to be overexpressed in breast cancer, we reasoned the transcription factors that drive WBP2 expression would have contributed to this phenotype, at least in part." (PMID 32393834, 2020). "In translational research, evidence supports the role of WBP2 as a biomarker for early detection, prognosis, and companion diagnostics in breast cancer." (PMID 32393834, 2020). "The role and the mechanism of WBP2 in regulating breast cancer response to trastuzumab were elucidated using in vitro PDXs and murine xenograft models." (PMID 32210163, 2020). "Consistently, miR-23a inhibitor upregulated endogenous WBP2 protein and mRNA expression, supporting the notion that miR-23a controls the basal state of WBP2 in breast cancer cells." (PMID 32820148, 2020). "The results showed that co-alterations of the MST1/2-miR-23a-WBP2 corelated with poorer survival in breast cancer patients." (PMID 32820148, 2020). "Collectively, the evidence further supports the notion of WBP2 as an oncogene that is downregulated by ITCH tumor suppressor-mediated proteasomal degradation in at least a subset of aggressive breast cancers." (PMID 32393834, 2020). "Tyrosine phosphorylation was the first posttranslational modification of WBP2 to be discovered in a phosphoproteomics study of breast cancer development." (PMID 32393834, 2020). "The results support the notion that MST is a rheostat that controls the basal level of WBP2 in a diverse molecular subtypes of breast cancer including the TNBC (MDA-MB-468, MDA-MB-436, MDA-MB-231, BT549, and MDA-MB-453)." (PMID 32820148, 2020). "ChIP experiments showed that USF-1 drives WBP2 transcription by binding to the E-box of WBP2 promoter, resulting in an increase of WBP2 transcript, protein level, and breast cancer cell proliferation." (PMID 32393834, 2020). "Increase in WBP2 protein expression was observed in 89% (8 out of 9) of the breast cancer cell lines studied." (PMID 32820148, 2020). "A Wnt pathway crosstalk is substantial in breast cancer; for example, in the Hippo pathway, a transcriptional coactivator called WW domain binding protein 2 (WBP2) forms a network with YAP, TAZ, and β-catenin, which then promotes TCF-induced malignancy." (PMID 31684152, 2019). "In human breast cancer, phosphorylation of WBP2 at Tyr192 and Tyr231 was regulated by c-Src and c-Yes kinases and was stimulated by EGF." (PMID 30001383, 2018). "A luciferase assay showed that overexpression of WBP2 augmented MDR1 reporter gene activity in MCF-7 cells, indicating that MDR1 expression was modulated by WBP2 in breast cancer cells." (PMID 29937544, 2018).
breast carcinoma (continued). "Our findings provide a novel insight into how ERα signalling regulates the response of ERα-positive breast tumours to chemotherapy, and to the best of our knowledge, is the first evidence of WBP2-mediated drug resistance in ERα-positive breast cancer cells." (PMID 29937544, 2018). "Since WBP2 participated in the process of doxorubicin resistance of breast cancer, we assessed the expression of several MDR molecules including MRP1, MDR1 and BCRP in MCF-7 and MCF-7 cells transfected with the WBP2 plasmid." (PMID 29937544, 2018). "We found a higher expression of WBP2 in breast cells than in normal breast epithelial cells, especially in highly aggressive breast cancer cells (MDA-MB-231 and SKBR3) or doxorubicin-resistant MCF7/ADR cells." (PMID 29937544, 2018). "We also evaluated WBP2 level in breast cancer patients and found WBP2 was moderately upregulated in ER-positive (n = 11) compared with ER-negative breast cancer patients (n = 4)." (PMID 29937544, 2018). "As a tyrosine kinase substrate, tyrosine phosphorylation of WBP2 at Try192 and Try231 stimulated by epidermal growth factor (EGF) can cause disturbances of cell proliferation regulation and induce tumorigenesis in breast cancer cells." (PMID 29497031, 2018). "The data presented here indicates that WBP2 contributes to chemoresistance in ERα-positive breast cancer cells, as shown in an in vivo animal model and in vitro cell experiments." (PMID 29937544, 2018). "This review interprets the relationship between WBP2 and breast cancer, and provides comprehensive views about the function of WBP2 in the regulation of the pathogenesis of breast cancer and endocrine therapy in breast cancer treatment." (PMID 28724435, 2017). "This indicates that WBP2 is not only a hub protein in breast cancer, but also a key regulator in other malignant carcinomas." (PMID 28724435, 2017). "TAZ is overexpressed in primary breast cancer and interacts with WBP2 via the WW-domain of TAZ and the C-terminal PPxY motif of WBP2, to enhance the migration of breast cancer cell lines." (PMID 28724435, 2017). "In this review, we focus on the correlation between WW domain binding protein 2 (WBP2) and breast cancer to reveal the essential functional regulatory role of WBP2 on the process of breast cancer." (PMID 28724435, 2017). "In breast cancer cells, WBP2 cooperates with β-catenin and YAP/TAZ to drive TCF-mediated gene transcription downstream of WNT signalling." (PMID 28332498, 2017). "WBP2 was firstly identified to be a novel tyrosine kinase substrate in the MCF10AT model of breast cancer, and further proved to be authentic target of Epidermal Growth Factor (EGF) signaling and Iressa." (PMID 28724435, 2017). "Most of the research on functions of WBP2 undertaken to date has distinctly clarified its role in breast cancer." (PMID 28724435, 2017). "Treatment with Iressa eliminates the increase of phosphorylated WBP2 induced by EGF in breast cancer cells, indicating that phosphorylation of WBP2 is an indispensable component of EGF signaling and the gefitinib pharmacogenomic pathway in breast cancer." (PMID 28724435, 2017). "As a transactivation coactivator of ER, WBP2 plays an effective role in ER-positive tissue or cell lines, such as breast tissue or ER-positive breast cancer cell lines." (PMID 28724435, 2017). "Both overexpression of WBP2 and activation of tyrosine phosphorylation upregulate the signal cascades in the cross-regulation of the Wnt and ER signaling pathways in breast cancer." (PMID 28724435, 2017). "As a coactivator of ERα/PR, WBP2 interacts with ERα directly and activates the expression of proliferation-related target genes to function in the development and progression of breast cancer." (PMID 28724435, 2017). "Using complementary MALDI- and ESI-based mass spectrometry, WBP2 has been determined to be a tyrosine kinase substrate during the development of breast cancer." (PMID 28724435, 2017).